IL10 (interleukin 10)
Diseases named in the same sentence as IL10 in open-access papers (continued):
Sharing a sentence is not in itself a finding about the gene and the disease.
adenoma (continued). "Expression changes detected by RNA-seq were validated in an expanded set of samples by RT-qPCR for IL10, SOX9, GBX2, and HOXA5, genes with biological functions that may contribute to the reduced progression of hyperplasia to adenoma." (PMID 33632299, 2021). "Moreover, in the adenoma patients there was no IL-10 involvement, while this parameter was implicated in the cancer patients' immune responses, suggesting that IL-10 may be prognostic for the passage from adenoma to cancer as a dual biomarker together with sIL-2R." (PMID 22235223, 2011). "Furthermore, cytokines that are known to promote (IL-12, IFN-γ, and IL-2) or regulate (IL-10, IL-4, and IL-17) T-cell polarization and differentiation were similar in the serum of individuals with and without detectable adenomas." (PMID 25884547, 2015). "We assessed the association between plasma endotoxin concentrations, plasma cytokines IL-4, IL-6, IL-8, IL-10, TNF-α, and interferon-γ (IFN-γ) levels, and local cytokine mRNA expression levels of IL-4, IL-6, IL-8, IL-10, IL-17, TNF-α, and IFN-γ in relation to adenomas." (PMID 23442743, 2013). "In the adenoma group, on the other hand, IFNγ and IL-6 pathways still partially regulated gender specific Th1 and Th2 cell network homeostasis but in neither sex was a significant relationship observed between IL-10 and other Th1/Th2 network components." (PMID 22235223, 2011). "Further confirmation also came from the finding that in adenoma patients, gender-specific pathways IFNγ and IL-6 still partially regulate immune response homeostasis in men and women and in neither sex was a significant relationship observed between IL-10 and the other Th1/Th2 network components." (PMID 22235223, 2011). "The over-expression of IL-4 and IL-10 in tissues was increased in CR adenomas versus healthy subjects and was only non-statistically higher in CRC than CR adenomas." (PMID 40149674, 2025).
airway hyperresponsiveness (20 papers, 2004 to 2025). "Specifically, lung‐delivered IL‐10 treatment mitigated LPS‐induced weight loss and airway hyperresponsiveness and improved lung compliance." (PMID 39980189, 2025). "LPS‐induced airway hyperresponsiveness as measured by lung resistance was decreased with IL‐10 (vs. vehicle) treatment at the 24 mg/mL methacholine dose (p < 0.0001)." (PMID 39980189, 2025). "Overexpression of IL-10 in the nasal mucosa of transgenic mice suppresses RSV replication in the respiratory tract, while ovalbumin-sensitized and challenged IL-10-/- mice develop airway hyperresponsiveness only if infected with RSV." (PMID 21910858, 2011). "IL‐10 reduced LPS‐induced airway hyperresponsiveness and improved lung compliance." (PMID 39980189, 2025). "Thus, the lower level of IL-10 and IL-13 may contribute to the mild airway hyperresponsiveness in March1−/− compared to WT mice." (PMID 29854835, 2018). "Concurrently, they induce regulatory T cells (Tregs) to secrete anti-inflammatory IL-10 and TGF-β, dampening airway hyperresponsiveness." (PMID 40352259, 2025). "Airway hyperresponsiveness as well as levels of IFN-γ, IL-13, IL-6, and IL-10 was lower in the lungs of asthmatic March1−/− mice compared to WT, whereas lung levels of TNF-α, IL-4, and IL-5 were not significantly different." (PMID 29854835, 2018). "Animal studies have suggested that interleukin (IL)-10 plays a critical role in the pathogenesis of RSV bronchiolitis and subsequent airway hyperresponsiveness." (PMID 21910858, 2011). "Although IL-10 did not improve airway remodeling in this model, it effectively attenuated airway hyperresponsiveness in corticosteroid-insensitive asthmatic mice." (PMID 41312367, 2025). "Experimental study showed that ablation of T cell–derived IL-10 increased the IFN-γ response to HDM, reducing IL-13 levels and airway eosinophilia without affecting IgE levels or airway hyperresponsiveness." (PMID 34930201, 2021). "Ablation of T cell–derived IL-10 increased the IFN-γ and IL-17A response to HDM, reducing IL-13 levels and airway eosinophilia without affecting IgE levels or airway hyperresponsiveness." (PMID 31445933, 2020).
anaphylaxis (20 papers, 2010 to 2025). An acute hypersensitivity reaction that occurs from exposure to an allergen. "Clostridium butyricum CGMCC0313 increases forkhead box P3 (FOXP3) Treg cells, TGF-β, and IL10, inverts the imbalance between Th1/Th2 and Th17/Treg cells, and reduces β-lactoglobulin-mediated intestinal anaphylaxis, thereby contributing to the reduction of the risk of allergy in mice." (PMID 33897683, 2021). "IL-10 expression was also significantly increased in Balb/c mice that developed systemic anaphylaxis." (PMID 35769569, 2022). "Cytokines, such as the tumor necrosis factor-α, interleukin (IL)-4, IL-5, and IL-10, act as the contributing mediators in the development of various anaphylaxis symptoms." (PMID 34169047, 2021). "Plasma cytokine levels were significantly higher after LPS, while increased IL-10 levels were seen after anaphylaxis." (PMID 22114895, 2011). "After anaphylaxis, we found upregulation of several proinflammatory cytokines, although high levels of circulating IL-10 were measured." (PMID 22114895, 2011). "In contrast, IL-10 mRNA levels were decreased in LPS and Ova treated mice and after anaphylaxis compared to controls." (PMID 22114895, 2011). "The expressions of interleukin 10 (IL‐10) and IL‐6 were significantly increased during anaphylaxis in patients with cystic echinococcosis, according to previous studies, and IL‐10 and IL‐6 play a crucial role in the occurrence and development of a variety of inflammatory diseases." (PMID 37647453, 2023). "Supporting these findings, in previous works applying identical SLIT with D1ManPrup3 in a similar Pru p 3-induced anaphylaxis mouse model, higher levels of Foxp3 were observed in the tolerant group compared to desensitized animals, which also translated into higher IL-10 levels." (PMID 37334360, 2023). "Furthermore, severe acute anaphylaxis episodes can occur in allergic patients with high IL-10 levels." (PMID 38067164, 2023). "For example, many dogs with anaphylaxis showed increased plasma IL-10 concentration, known to increase within an hour of shock or endotoxaemia, and some dogs showed elevated plasma IL-6 or CCL2, known to increase within 1–3 h of shock, endotoxaemia or surgical stimulus." (PMID 36003410, 2022). "Although we implied possible involvement of impaired regulatory immune responses in anaphylaxis patients, we did not measure IL‐10 or regulatory T cells in association with IgG4." (PMID 36086810, 2022). "Another study performed to characterize serum biomarkers during anaphylaxis in the emergency department patients identified elevated IL-6 and IL-10 levels, which could be a unique signature of anaphylaxis." (PMID 34575019, 2021). "In this study involving β-lactoglobulin-induced anaphylaxis in mice, it was shown that oral administration of a recombinant L. lactis delivering IL-10 gastrointestinally prior to sensitization was able to induce immunotolerance towards the allergen, thus reducing food-induced anaphylaxis." (PMID 28376880, 2017). "In patients who had anaphylaxis, concentrations of IL-6 and IL-10 remained elevated for up to 24 hours after the initial dose of antivenom, whereas concentrations of TNFα and sTNFRI returned to baseline levels between 10–15 hours after the initial dose of antivenom." (PMID 23936562, 2013). "Similarly, patients with both pyrogenic reactions and anaphylaxis had significantly higher peak concentrations of IL-6, IL-10, TNFα and sTNFRI compared to patients with severe anaphylaxis alone." (PMID 23936562, 2013). "In this context, IL10 might be a good candidate molecule in Treg-mediated control of anaphylaxis." (PMID 23922690, 2013). "Both IL-10 and CCL2 concentrations were significantly higher in the anaphylaxis group (IL10 P < 0.0001, CCL2 P = 0.007) and the critical illness group (IL10 P = 0.007, CCL2 P < 0.001), compared to the healthy group." (PMID 36003410, 2022).
anaphylaxis (continued). "We have previously demonstrated the presence of IL-10-producing CD5+ B cells and suggested their potential role in regulating cow’s milk casein allergy in humans and IgE-mediated anaphylaxis in mice." (PMID 26785945, 2016). "Sharply elevated, rather than reduced, IL-10 levels were evident amongst 36 patients who presented to emergency departments with severe acute anaphylaxis episodes." (PMID 20567520, 2010). "That anaphylaxis-associated hypothermia can be modulated without any change of histamine levels is reminiscent to another study using the same model of IgE-mediated PSA, in which reduced hypothermia induced by IL-10 overexpression was not matched by changes in serum histamine." (PMID 23922690, 2013).
aneurysm (20 papers, 2007 to 2025). Bulging or ballooning in an area of an artery secondary to arterial wall weakening. "High levels of IL-10 have been linked to abdominal aortic aneurysm formation, where the IL-10 genotype AA at −1082 increases risk of aneurysm formation." (PMID 31908741, 2019). "Additional larger controlled studies are necessary to clarify the association of IL-10 with aneurysm formation and rupture and the role of IL-10 after SAH, including its prognostic and diagnostic predictive potential for SAH outcomes." (PMID 28659854, 2017). "In some AAA patients, plasma levels of IFN-γ, IL-17A, and C-reactive protein are positively correlated with the cross-sectional area of AAA, while IL-10 is positively correlated with the growth rate of the aneurysm, and increased CRP levels indicate an increased risk of death in AAA patients." (PMID 38111889, 2023). "A similar pattern was seen for IFNγ and IL10, indicating that solTNF inhibition reduced the inflammatory response in the aneurysm wall." (PMID 36186984, 2022). "It has been reported that high levels of IL-10 are detected in the serum of patients with aneurysms and that IL-10−/− counteracts Ang II-induced vascular dysfunction in APOE−/− mice." (PMID 32509885, 2020). "This view of Th1-directed aneurysm and later increase of IL-10 and Th2-directed response is in line with the known anti-inflammatory properties of IL-10, as has been suggested." (PMID 17940614, 2007). "It was demonstrated that plasma IL-10 remains significantly positively correlated with the annual AAA expansion rate in a multivariate analysis of 386 AAA patients after correcting for putative aneurysm confounding factors and baseline AAA diameters." (PMID 34572424, 2021). "Clinical and experimental studies carried out in abdominal aortic aneurysms byhistological and immunohistochemical procedures proved that a predominantTh2-mediated immune response, mainly driven by IL-4, IL-5, or IL-10 cytokines,induces severe aneurysm formations." (PMID 30810667, 2019). "Thus over-expression of IL-10 could, in this scenario, inhibit the Th1 response and increase the Th2 contribution, leading to the development of aneurysm." (PMID 17940614, 2007). "In a transgenic mouse model, the augmentation of the systemic IL-10 expression reduced both the development of AAA and the rate of dissecting aneurysm." (PMID 33808169, 2021). "In the wall of an AAA there is up-regulation of pro-inflammatory IL-1β, IL-6, IL-10 and TNF-α, which have been shown to positively correlate with aneurysm growth." (PMID 20964810, 2010). "Previous reports revealed that both IL-10 and TGF-β could promote VSMC proliferation and elastin expression, thus counteracting aneurysm progression." (PMID 35228523, 2022). "IL-10, an anti-inflammatory cytokine, was also increased, regardless of aneurysm presence, contributing to the recognized anti-inflammatory effects of MSCs." (PMID 31428158, 2019). "One study reported that IL-10 mRNA expression was virtually non-existent in aneurysm walls, although it was present in the walls of temporal artery controls." (PMID 28659854, 2017). "In addition, the mRNA levels of the anti-inflammatory cytokine IL-10 in the aneurysms were not significantly different, nor were mRNA levels of iNOS used as an indicator of M1 macrophages in the aneurysms." (PMID 35203568, 2022). "Significantly higher levels of IL-6 and IL-10 were observed in patients who did not respond to IVIG and in those who developed aneurysms in CA." (PMID 41441313, 2025).
celiac disease (20 papers, 2006 to 2025). An autoimmune genetic disorder with an unknown pattern of inheritance that primarily affects the digestive tract. "In this study we have performed a case-control and a familial study to assess the involvement of IL-10 polymorphisms in celiac disease." (PMID 16579847, 2006). "In addition, IL-10 polymorphisms are correlated with more severe mucosal damage and early-onset of celiac disease, even though IL-10 secretion abnormalities are suggested to be more a cause than a consequence of this disease." (PMID 31178867, 2019). "Moreover, the Th2-associated cytokines IL-5, IL-10 and IL-13 were elevated in children with coeliac disease compared to controls." (PMID 25212572, 2015). "In fact, low levels of IL-10 have been found associated with different typical features of celiac disease such as anti-tissue transglutaminase antibodies and studies using recombinant human IL-10 (rhIL-10) have shown a suppression of gliadin-specific T cell activation." (PMID 16579847, 2006). "The strong influence of HLA-DQA1*0501 and DQB1*02 (HLA-DQ2) on the development of celiac disease could be masking a potentially weak effect of IL-10 polymorphisms on CD." (PMID 16579847, 2006). "This strain has been described to reduce the inflammatory effects of the dysbiotic intestinal microbiota of individuals with coeliac disease on peripheral blood mononuclear cells partially via the induction of IL-10 production." (PMID 31013929, 2019). "In the SI crypt hyperplasia is a general sign of inflammation, which is not only observed in Il10−/− mice, but also in patients with celiac disease or IBD." (PMID 27027442, 2016). "A higher concentration of IL-10 was measured in the media exposed to control explants compared to celiac disease in remission or gluten sensitivity." (PMID 25734566, 2015). "The anti-inflammatory cytokine IL-10, known as an important immunomodulator of the intestinal tract 24, has in former studies been both up-regulated 3,25 as well as unchanged 4,5 in coeliac disease patients compared to controls." (PMID 25212572, 2015). "The study showed a significant increase in several cytokines including TNF-α, IFN-γ, IL-6 and IL-10: all crucial in the pathogenesis of celiac disease." (PMID 25326000, 2015). "It has been described occasionally an increase in IL-10 mRNA levels in the intestine of celiac disease patients, but it is possible that this is a counter-regulatory mechanism triggered by the disease, and not the cause of the pathology." (PMID 16579847, 2006). "With the exception of IL6 and IL10, all serum cytokines analysed at 36 months showed a significant and strong correlation (Pearson’s coefficient r > 0.5) with gluten intake over the second year of life in children who developed celiac disease." (PMID 35354862, 2022). "For example, IL-10 concentration is significantly higher in celiac disease sera." (PMID 31178867, 2019). "Of note however, the production of IL-10 (along with IFN-γ) in the duodenum during active celiac disease has been reported elsewhere, indicating that the post-challenge IL-10 production may be part of a normal celiac response." (PMID 21949691, 2011). "There have been few studies of IL-10 polymorphisms with celiac disease, mostly with negative results." (PMID 16579847, 2006). "Interleukin-10 polymorphisms do not seem to be involved in celiac disease predisposition in the Spanish population." (PMID 16579847, 2006). "Serum samples were collected in 19 of 26 children with coeliac disease after starting a gluten-free diet after 1·5 ± 0·36 years [median ± standard deviation (s.d.)] and analyses performed for cytokines IFN-γ, IL-5, IL-10, IL-12p70 and IL-13." (PMID 25212572, 2015). "Our finding of cytokines IL-5, IL-10 and IL-13 belonging to the Th2 response being elevated significantly in coeliac disease was surprising, as a Th2 cytokine pattern has not been considered previously to be central in the immune reaction in coeliac disease." (PMID 25212572, 2015).
celiac disease (continued). "Therefore, IL-10 is considered as a candidate for the treatment of TH1-mediated autoimmune disorders such as inflammatory bowel disease and celiac disease." (PMID 25705619, 2014). "Interleukin-10 and IFN-γ ELISPOT assays for detection of gliadin specific T-cell lines indicates that recombinant human IL-10 abrogated the IFN-γ response to gliadin in patients with celiac disease." (PMID 24710420, 2012). "This speculation would be in line with a previous finding of significantly higher levels for IL-6, IL-13, IL-10, IL-1b, and TNF-α in combination with significantly lower 25(OH)D concentrations in screening-detected celiac disease cases compared with healthy controls." (PMID 34604278, 2021). "IL-13, but not IL-10, was found elevated in a study of refractory coeliac disease." (PMID 25212572, 2015).